CLU (clusterin)
Diseases named in the same sentence as CLU in open-access papers (continued):
Sharing a sentence is not in itself a finding about the gene and the disease.
retinoblastoma (1 paper, 2015). A malignant tumor that originates in the nuclear layer of the retina. "Furthermore, CLU may influence cellular apoptosis in neoplastic cells, as recently shown in retinoblastoma cells, in which overexpression of CLU was associated with enhanced cellular apoptosis." (PMID 25934174, 2015).
Sézary syndrome (1 paper, 2020). "Another study followed that 105 cases of MF and Sézary syndrome's tissue sections were immunostained for clusterin." (PMID 33299887, 2020).
Skin Cutaneous Melanoma (1 paper, 2022). "By utilizing GEPIA2’s module “Pathological Stage Plot” to evaluate the relationship between CLU expression and the pathological staging of malignancies such as KICH, KIRC, LIHC, LUAD, Skin Cutaneous Melanoma (SKCM), THCA, and UCS (all p < 0.05), excluding others." (PMID 36685863, 2022).
sleep disorder (1 paper, 2018). A change from the patient's baseline sleeping pattern, in the hours slept and/or an alteration/dysfunction in the stages of sleep. "Expression of four proteins including PKM, CLU, KNG1 and PFN1 were changed by CSD and these proteins can potentially serve as biomarkers for sleep disorders." (PMID 30235220, 2018).
soft tissue tumors (1 paper, 2017). "In order to compared the performance of FDCSP and SRGN with known FDC-S markers in the differential with soft tissue tumors, we tested CD21, CD23, CD35, CXCL13, Clusterin, Claudin 4 and Podoplanin in our groups of tumors and controls." (PMID 28145886, 2017).
synovitis (1 paper, 2022). Inflammation of a synovial membrane. "More specifically, it has been shown that CLU mRNA and protein levels were both associated with synovitis severity in knee OA." (PMID 35705674, 2022). "CLU mRNA and protein levels were both associated with synovitis severity." (PMID 35705674, 2022). "In the present study, we found that a multifaceted protein related to apoptosis and inflammation, CLU, was expressed in the systemic and local joint environment of knee OA patients, especially the patients with high-grade synovitis and was positively associated with degree of synovitis." (PMID 35705674, 2022). "After adjusting for age, gender, and BMI, multivariate logistic regression analysis attested a direct link between CLU mRNA expression in knee OA synovium and degree of synovitis (β coefficient = 0.126, 95% CI 0.098–0.173, P < 0.001)." (PMID 35705674, 2022). "All our findings led us to postulate that increases in CLU mRNA and protein levels in the systemic and local joint environment would reflect severity synovitis of knee OA." (PMID 35705674, 2022). "In addition to CLU protein and mRNA expressions in knee OA synovitis, its protein levels in the circulation and synovial fluid of knee OA patients with different synovitis groups were further determined." (PMID 35705674, 2022). "Taken together, our data support the notion that CLU could exert its anti-inflammatory action in synovitis and might have potential as a novel therapeutic target for preventing or delaying disease progression of knee OA." (PMID 35705674, 2022). "These previous results were confirmed by the present study, which denoted up-regulation of CLU protein and mRNA expressions in knee OA synovium, particularly in the inflamed synovium and remarkable increases in its protein levels in plasma and joint fluid of knee OA patients with synovitis." (PMID 35705674, 2022). "In a clinical study, compared with knee OA patients without synovitis, CLU protein and mRNA were expressed in the synovium of knee OA patients with synovitis, especially those with high-grade, consistent with analyses of its plasma and synovial fluid levels." (PMID 35705674, 2022).
systemic amyloidosis (1 paper, 2019). "Both apoE and CLU are representative signature proteins in various types of systemic amyloidosis." (PMID 30691533, 2019).
tendinopathy (1 paper, 2014). "In ACL, the anti-apoptotic proteins clusterin and annexin A5 were enriched, both of which have previously been identified in tendinopathy." (PMID 24818782, 2014).
thyroid (1 paper, 2015). "Previous data suggested that CLU expression in thyroid malignant cells was modified in vitro and in vivo, and that there was a complex mechanism of regulation of CLU expression in the normal and cancerous thyroid tissue." (PMID 25934174, 2015).
thyroid nodule (1 paper, 2015). A small circumscribed mass in the THYROID GLAND that can be of neoplastic growth or non-neoplastic abnormality. "Our results suggest the existence of a specific alteration of CLU2:CLU1 ratio towards CLU2, thus providing the first circumstantial evidence for the potential use of CLU transcript variants as effective biomarkers for a more accurate assessment of the so called “indeterminate” thyroid nodules." (PMID 25934174, 2015).
thyroid tumour (1 paper, 2015). "Moreover, potential quantitative changes in CLU transcript variants expression were investigated by means of qPCR as reported in Materials and Methods in the thyroid tumour tissues in comparison to the corresponding normal tissues isolated from the same patients." (PMID 25934174, 2015).
transitional bladder cell carcinoma (1 paper, 2020). "Abnormal expression of CLU has also been reported in patients with transitional bladder cell carcinoma, which might act as a diagnostic and prognostic biomarker for the disease." (PMID 32039450, 2020).
vitiligo (1 paper, 2022). Generalized well circumscribed patches of leukoderma that are generally distributed over symmetric body locations and is due to autoimmune destruction of melanocytes. "Regarding the role of endothelial cells in vitiligo, human dermal microvascular endothelial cells secrete copious amounts of clusterin." (PMID 34839983, 2022).
Von Willebrand disease (1 paper, 2024). von Willebrand disease (VWD) is a hereditary bleeding disorder caused by a genetic anomaly leading to quantitative, structural or functional abnormalities of the Willebrand factor (von Willebrand factor; VWF). "We identified clusterin (CLU) as a potential candidate regulator of VWF based on a single cell RNA sequencing (scRNA-seq) analysis in control endothelial cells (ECs) and von Willebrand disease (VWD) endothelial colony-forming-cells (ECFCs)." (PMID 38363768, 2024).
tumor (215 papers, 2003 to 2026). "Studies have shown that CLU expression is associated with various clinicopathological features, including tumor grade and patient survival outcomes." (PMID 40606578, 2025). "Extensive evidence has linked an increase in CLU expression with an increase in tumour severity and treatment resistance." (PMID 38319453, 2024). "A positive correlation was identified between CLU expression and tumour severity with elevated expression of CLU also associated with a decrease in disease-free survival in CRC." (PMID 38319453, 2024). "ADIRF, tumor-associated genes CLU, FAM13C, as well as NGF, PRELP, RERG, PTGIS, GPC3 genes were among the top 20 overexpressed genes in EcE stromal cell population." (PMID 39169201, 2024). "This shift in the expression of CLU isoforms is linked to increased tumour cell survival, aggressiveness and enhanced metastatic potential." (PMID 38319453, 2024). "It is important to note that the study that reported tumor-associated stromal clusterin in relation to therapy response also considered patients with a limited amount of residual tumor (residual cancer burden (RCB) score 1) as good responders." (PMID 36769287, 2023). "Chemotactic mediated bacterial targeting and accumulation within tumor’s has been associated with tumor hypoxic micro- environment, pre- dominant expression of clusterin, serglycin, TGF- β2 etc." (PMID 38090593, 2023). "In human colon carcinoma, the translocation of CLU from the nucleus to the cytoplasm has been directly linked to tumor progression." (PMID 37685987, 2023). "Forest plots revealed that both CLU expression and tumor grades were independently associated with the prognosis of LGG patients." (PMID 37686218, 2023). "Herein, immunological infiltration of distinct tumor-related immunological cells was associated with CLU expression in CAFs and CD8 + T cells." (PMID 36685863, 2022). "Some of the identified proteins have been shown to inhibit apoptosis or cause tumor cells to adapt to hypoxia, thereby promoting tumor cell survival, including clusterin, CD5L, HYOU1, prosaposin, and hepatocyte growth factor activator." (PMID 35659255, 2022). "A change in the balance between the isoforms of clusterin is tightly controlled in the cell during different steps of tumor progression associated with changes in apoptotic, proliferative, and invasive processes." (PMID 33805203, 2021). "CLU action during carcinogenesis is a continuous field of study since CLU has been implicated in tumor cells survival, epithelial–mesenchymal transition, metastasis and chemoresistance." (PMID 33744871, 2021). "This implies that, for some tumours, the underlying mechanisms of CLU in regulating their occurrence and development are identical." (PMID 33521130, 2021). "In mouse PCa xenografts, IL-24 decreases the levels of secreted soluble clusterin (sCLU) protein, which is linked to resistance to chemotherapy and radiation and hormone therapies, leading to reduced tumor growth and angiogenesis." (PMID 30669553, 2019). "The inactivation of the clusterin gene (CLU), deleted in ~55% of TCGA cases, was associated with neoplastic transformation and tumor progression, while downregulation of MX1 was involved in proliferation, progression and metastasis of PC cells." (PMID 30925701, 2019). "Our data suggest that clusterin is an important protein associated with both cancer therapy and tumor development." (PMID 26293319, 2015). "CLU is a sulphated glycoprotein, implicated in various cell functions involved in carcinogenesis and tumor progression, including cell cycle regulation, cell adhesion, DNA repair and apoptosis." (PMID 17989776, 2007). "CLU (Clusterin) is a stress-activated, ATP-independent molecular chaperone and is associated with the development of different physiological and pathological processes, including carcinogenesis and tumor progression." (PMID 38789729, 2024).
tumor (continued). "For example, CLU modulates the chemotactic migration and polarization of tumor-associated macrophages (TAM) by regulating the secretion of chemotactic cytokines, and it modulates the recruitment of dendritic cells (DCs) by regulating the expression of chemokine CCL20." (PMID 37686218, 2023). "Overexpression of CLU has been observed in various human cancers, making it a potential therapeutic target and a valuable research opportunity for understanding the underlying mechanisms of tumor progression." (PMID 37685987, 2023). "PRUNE2 (B-cell CLL/lymphoma 2 and adenovirus E1B 19 kDa interacting family) and CLU, encoding Clusterin a secreted chaperone, were also identified and have been shown to operate in cell death, cell transformation, tumour progression and neurodegenerative disorders." (PMID 35061738, 2022). "Several research has gathered evidence that changes in Clusterin expression may be directly associated with tumor metastasis." (PMID 36176404, 2022). "Overall, our pan-cancer research suggests that Clusterin expression levels are linked to tumor carcinogenesis and prognosis, which contributes to understanding the probable mechanism of Clusterin in tumorigenesis as well as its clinical prognostic significance." (PMID 36685863, 2022). "CLU has been associated with carcinogenesis and tumor growth in various cell types." (PMID 36685863, 2022). "Altogether, these data suggest that CLU expression may be required to limit the excessive activation of NF-κB that occurs during chronic inflammation associated with tumor growth." (PMID 34360868, 2021). "For example, it has been shown that, during oncogenic transformation, tumor cell survival is associated with increased expression of the secretory form of clusterin and significant decrease in the level of expression of the nuclear form of clusterin." (PMID 33805203, 2021). "CLU is a multifunctional molecule that has been implicated in tumorigenesis and tumor progression." (PMID 33054843, 2020). "Another protein firmly implicated in carcinogenesis and tumour progression is Clusterin (CLU)." (PMID 29286311, 2017). "These evidences suggest up-regulation of clusterin is associated closely with tumor progression." (PMID 26293319, 2015). "CLU function is considered enigmatic, as it has been associated with various contradictory roles in cellular function, including cell apoptosis, tumorigenesis, and tumor progression." (PMID 25574066, 2014). "High baseline TILs together with low stromal clusterin expression were associated with a higher likelihood of achieving a complete pathological response, which was independent from other clinico-pathological parameters, such as age, tumor/nodal stage or histological subtype." (PMID 36428702, 2022). "The burden of functional connection of CD59 with CLU may enhance its value due to association with cell lysis resistance and, consequently, the encouraging of tumor growth, but an expression of different CD antigens and their implication in tumor expansion remains uncertain." (PMID 32023884, 2020). "Moreover, CLUKO mice are more susceptible than WT to chemically induced skin tumorigenesis, suggesting that CLU might negatively modulate epithelial cell transformation." (PMID 31885575, 2019). "Indeed, CLU has been implicated in numerous physiologic and pathologic processes important for carcinogenesis and tumour growth, including apoptotic cell death, cell cycle regulation, DNA repair, cell adhesion, tissue remodeling, lipid transportation, membrane recycling and immune system regulation." (PMID 25934174, 2015). "S100A6, a calcium-binding protein of the S100 family, localizes primarily to the cytoplasm of tumor cells, while CLU, a multifunctional protein, is significantly upregulated under cellular stress in diseases including cancer." (PMID 41009818, 2025).
tumor (continued). "The CLU mRNA expression in 519 LGG, 163 GBM and 208 normal brain tissues was analyzed, the level of CLU in tumor tissues was significantly higher than that in normal tissue." (PMID 40606578, 2025). "Histological and immunohistochemical analyses confirmed the role of CLU in tumor formation through BCL2L1 upregulation." (PMID 40606578, 2025). "WDR5–MYC complexes drive super-enhancer formation at oncogenic loci, whereas EZH2-mediated PRC2 activation silences tumor suppressors such as CLU and CADM1." (PMID 40787450, 2025). "Extensive research suggests that CLU’s diverse isoforms contribute to several physiological processes, such as tumorigenesis, programmed cell death, tumor metastasis, invasion, and epithelial–mesenchymal transition." (PMID 40573993, 2025). "CLU is frequently upregulated in various human cancers and contributes significantly to tumor progression, chemoresistance, and metastasis." (PMID 39627493, 2025). "CLU is involved in several tumor-promoting processes, including apoptosis resistance, stress adaptation, and metastasis." (PMID 40573993, 2025). "On the other hand, CLU plays a complex role in cancer, exhibiting both tumor-promoting and tumor-suppressing properties, depending on the type of cancer." (PMID 39627493, 2025). "In vivo and in vitro CXCL8 and CLU expression levels in tumor cells were determined using qPCR, immunohistochemistry and ELISA." (PMID 39905539, 2025). "CLU silencing holds significant promise in the context of tumor biology due to its multifaceted role in cancer progression, therapy resistance, and metastasis." (PMID 40573993, 2025). "By silencing CLU, the protective mechanisms that enable tumor cells to survive and proliferate under hostile conditions can be disrupted." (PMID 40573993, 2025). "In cancer, such epigenetic interventions can modulate the role of CLU in cell survival and apoptosis, potentially reducing tumor growth and metastasis." (PMID 39253532, 2024). "The ability of CLU inhibition to induce senescence in cancer cells provides a valuable therapeutic approach to interrupt tumor growth." (PMID 39253532, 2024). "High CLU expression has been associated with several adverse outcomes in CRC including poor patient prognosis, tumour metastasis and chemotherapy resistance." (PMID 38319453, 2024). "In cancer, CLU has emerged as an aggressive player that promotes tumor growth, inhibits apoptosis and confers resistance to therapies." (PMID 39253532, 2024). "An analysis of TNBC tumor samples revealed a significant elevation and positive correlation between CLU and PRKD3 protein levels." (PMID 38473804, 2024). "CLU (clusterin) is a stress-induced molecular chaperone, highly expressed in aggressive cancer types, regulating multiple aspects of tumor development such as growth, metastasis, epithelial-mesenchymal transition, inflammation and survival pathways." (PMID 38447939, 2024). "Expression of CLU was significantly reduced in tumor tissue in a majority of cancers, while it was significantly elevated in the tumor tissues of KIRC, KIRP, THCA, and GBM." (PMID 37686218, 2023). "Normal tissues of LGG samples were absent in TCGA database, therefore expression of CLU in LGG was analyzed based on the tumor tissues in TCGA and the normal tissue in GTEx, and elevated expression of CLU in tumor samples than normal samples was observed." (PMID 37686218, 2023). "Yet, it also causes an increase in the levels of heat shock proteins, such as Hsp27 and CLU, which have the potential to promote the survival of tumor cells and resistance to treatment." (PMID 37685987, 2023). "The overexpression of CLU in epithelial ovarian cancer cells promotes tumor angiogenesis via VEGF secretion." (PMID 37685987, 2023). "The results from the overexpression showed that tumor cells growth rapidly increased and metastasized to the lungs, suggesting significant role of CLU is tumor growth." (PMID 37268731, 2023).